CDK4 (cyclin dependent kinase 4)
Diseases named in the same sentence as CDK4 in open-access papers (continued):
Sharing a sentence is not in itself a finding about the gene and the disease.
Myalgia (2 papers, 2021 to 2023). "Myalgia incidence was reported in only two of the trials of CDK4/6 inhibitors in the adjuvant setting." (PMID 37293258, 2023). "The incidence of myalgia was also decreased by the addition of CDK4/6 inhibitors to endocrine treatment, consistent with arthralgia rate." (PMID 33530456, 2021). "In Phase III trials exploring CDK4/6 inhibitors in the metastatic setting, myalgia rate was 4.8–11.9% in patients receiving CDK4/6 inhibitors and AIs." (PMID 33530456, 2021). "Myalgias, back pain and bone pain also tended to be reduced in patients treated with CDK4/6 inhibitors." (PMID 33530456, 2021). "Myalgias occurred in 2–23.7% of patients receiving AIs compared with 4.8–11.9% of patients treated with CDK4/6 inhibitors." (PMID 33530456, 2021).
myoepithelial carcinoma (2 papers, 2019 to 2025). "Key proteins in cell cycle regulation, including c-myc, p21, Cdk4, and Cyclin D3, were all recently documented as potential prognostic factors in myoepithelial carcinoma of salivary glands." (PMID 31827554, 2019). "CCND2 overexpression has not been described previously in myoepithelial carcinoma and we found only one reference to immunohistochemical expression of CDK4 in this disease." (PMID 40379813, 2025).
osteoporosis (2 papers, 2021). A condition of reduced bone mass, with decreased cortical thickness and a decrease in the number and size of the trabeculae of cancellous bone (but normal chemical composition), resulting in increased fracture incidence. "It is interesting to note that miR‐34s serve as an inhibitor in osteoblast proliferation by decreasing levels of Cyclin D1, CDk4, and CDK6 and a suppressor in osteoblast differentiation by decreasing SATB2 to facilitate the progression of osteoporosis." (PMID 33434305, 2021). "Osteoporosis incidence failed to reach the frequency threshold of 5% in trials of both AI monotherapy and CDK4/6 inhibitors in the metastatic setting." (PMID 33530456, 2021).
ovarian serous carcinoma (2 papers, 2020 to 2021). "In a trial enrolling mostly patients with serous ovarian carcinomas, the response rate to CDK4/6 inhibition was only 4% using RECIST criteria, although stable disease was commonly observed." (PMID 33947352, 2021).
Pancytopenia (2 papers, 2021 to 2024). An abnormal reduction in numbers of all blood cell types (red blood cells, white blood cells, and platelets). "Herein, we report the clinical history of a young woman with HR-positive HER2-negative metastatic BC and a pancytopenia due to carcinomatosis of the bone marrow receiving letrozole and leuprorelin plus the CDK4/6 inhibitor palbociclib, who significantly derived clinical benefit from treatment." (PMID 34692469, 2021).
pheochromocytoma (2 papers, 2015 to 2023). "Somatic mutations in exon 3 of the p18INK4c-encoding gene disrupting p18INK4c interaction with CDK4 or CDK6 were also detected in MTC and pheochromocytoma patients." (PMID 25900242, 2015).
pneumonia (2 papers, 2021 to 2024). An acute, acute and chronic, or chronic inflammation focally or diffusely affecting the lung parenchyma, caused by an infection in one or both of the lungs (by bacteria, viruses, fungi, or mycoplasma.). "ARSs are generally used for protein synthesis and interact with proteins in the mTORC1, GCN2, CDK4, and vascular endothelial growth factor receptor (VEGFR) signaling pathways and are potential markers of pneumonia." (PMID 38535310, 2024).
primary effusion lymphoma (2 papers, 2017 to 2022). A large B-cell lymphoma located in the body cavities, characterized by pleural, peritoneal, and pericardial fluid lymphomatous effusions and that is always associated with human herpes virus-8 (HHV-8). "Of note, p27KIP1 is also directed to proteasomal degradation in primary effusion lymphoma (PEL) by KSHV viral proteins, K-cyclin and V-cyclin, which are homologs of human cyclin D2 and form a complex with CDK4/6." (PMID 29160853, 2017).
rectum adenocarcinoma (2 papers, 2021 to 2022). An adenocarcinoma arising from the rectum. "Unlike the aberrant expression of CDK-1 in stage-2 colon and rectum adenocarcinoma being associated with a higher risk of metastasis, mutations in the catalytic subunit of CDK-4 gene has also been reported to be common and its abnormal expression has been uncovered in over 90 % of all bowel cancers." (PMID 33732631, 2021). "Heterozygous amplifications of ETS2 and CDK6 in TGCT; CDK6 in GBM; E2F1 and ID1 in rectum adenocarcinoma (READ); and SP1, CDK4, and MDM2 in ACC were all greater than 70%." (PMID 35911954, 2022).
retinal degeneration (2 papers, 2021 to 2022). Degeneration of the retina. "Altogether, these results reveal successive emergences of H3K27me3h and CDK4 prior cell death (TUNEL positive) suggesting that EZH2 is involved in an intermediate stage of retinal degeneration." (PMID 34502238, 2021). "H3K27me3 accumulation occurs between early (accumulation of cGMP) and late (CDK4 expression) events of retinal degeneration." (PMID 34502238, 2021). "A previous study demonstrated the expression of cell cycle proteins, such as cyclin dependent kinase 2 and cyclin dependent kinase 4, in rd1, but details of CDK1 expression during retinal degeneration have, to our knowledge, not been reported." (PMID 35883586, 2022).
rheumatoid arthritis (2 papers, 2021 to 2024). A chronic, systemic autoimmune disorder characterized by inflammation in the synovial membranes and articular surfaces. "CDK4 is a type of cyclin-dependent kinase, its inhibitor gene p16 (INK46a) can inhibit rheumatoid arthritis in synovial tissue, in which macrophages are the main source of inflammatory cytokines." (PMID 34120619, 2021).
salivary gland tumors (2 papers, 2015 to 2018). "They reported that expression of cyclin D1, CDK4 and CDKN2A were significantly higher in malignant salivary gland tumors (including adenoid cystic carcinoma and mucoepidermoid carcinoma) when compared to normal salivary gland." (PMID 26247885, 2015). "The second most common aberrations involved the cyclin pathway (CCND1, CDK4/6 or CDKN2A/B), which was abnormal in 26.5% of patients (31/117) with salivary gland tumors." (PMID 26247885, 2015).
sarcomatoid carcinoma (2 papers, 2014 to 2018). A malignant epithelial neoplasm characterized by the presence of spindle cells and anaplastic morphologic features. "As other immunohistochemical markers were negative, including CD45, CD163, CD68, Desmin, Myogenin, Melanoma, S100, α-SMA, Cytokeratin 7, Cytokeratin 20, MDM2 and CDK4, the tumors were diagnosed as sarcomatoid carcinomas." (PMID 29874846, 2018).
serous ovarian cancer (2 papers, 2018 to 2022). "The expression of SIRT2 is decreased in serous ovarian cancer, and down-regulation of SIRT2 promotes the expression of cyclin-dependent kinase 4 (CDK4), thereby promoting the proliferation, migration and invasion of serous ovarian cancer cells in vitro." (PMID 36505774, 2022).
smooth muscle tumor (2 papers, 2014 to 2025). A benign or malignant myomatous neoplasm arising from smooth muscle.
teratoma (2 papers, 2020). A non-seminomatous germ cell tumor characterized by the presence of various tissues which correspond to the different germinal layers (endoderm, mesoderm, and ectoderm). "Nevertheless, CDK4/6 inhibition seems to be promising in treating especially mature teratomas, including teratomas with malignant transformation." (PMID 32418994, 2020). "Further investigation of CDK4/6 inhibition for the treatment of teratoma is required based on the preliminary results indicating the safety and potential clinical benefit." (PMID 32455595, 2020).
tick-borne diseases (2 papers, 2022). "Additionally, high levels of kinases, including PKA, PKC, and CDK4, are observed in the plasma of patients infected with tick-borne diseases." (PMID 35456059, 2022). "Additionally, in the plasma of patients infected with the examined tick-borne diseases, glutathionylated kinases, including PKA, PKC, and CDK4, are found in high levels." (PMID 35457192, 2022).
tongue cancer (2 papers, 2021 to 2025). A malignant neoplasm affecting the tongue. "Red rectangles represent the hit genes involved in the treatment of tongue cancer (TERT, Bcl-2, CDK4/6, CDK2, VEGF, ER, RXR,c-KIT, MET, FGFR, PPAR8, PFFP, MMPs, CDK4, AR, F2, IGFR)." (PMID 39863836, 2025).
acute liver failure (1 paper, 2023). Rapid deterioration of liver function causing encephalopathy and coagulopathy. "In the second model in which C57/B6 mice were injected with a single dose of acetaminophen (APAP) to induce acute liver failure, similar observations were made that Trib1 expression was down-regulated at 1d and 2d in the liver after APAP injection, which mirrored PCNA/cyclin D1/CDK4 up-regulation." (PMID 37355685, 2023).
aneuploidy (1 paper, 2025). Chromosomal disorder consisting of the presence a chromosomal abnormality in which there is an addition or loss of chromosomes within a set. "While CDK4/6i only modestly increase CIN, we found that their efficacy in Rb-intact breast cancer cell lines is associated with increased baseline aneuploidy, an indicator of CIN." (PMID 39826695, 2025).
aortic stenosis (1 paper, 2025). Aortic valve stenosis is a aortic valve disease caused by the incomplete opening of the aortic valve. "Knockdown and overexpression studies provided deeper insights into the mutual regulation mechanisms between USP14 and CDK4, suggesting that these proteins might synergistically influence the pathogenesis of aortic stenosis." (PMID 40988122, 2025).
aortic valve stenosis (1 paper, 2025). Aortic valve stenosis (AVS) is a condition characterized by narrowing of the heart's aortic valve opening. "The expression of USP14 and CDK4 was significantly higher in aortic valve stenosis (AVS) tissues compared to control (CON) tissues." (PMID 40988122, 2025).
Atrophy (1 paper, 2023). Any weakening or degeneration, especially through lack of use. "Although CDK6 deficiency can cause thymic atrophy due to a block in the double-negative (DN) to double-positive (DP) stage of T cell development, there are no overt defects in immune cell development reported for CDK4-deficient mice." (PMID 37893220, 2023).
B-cell acute lymphoblastic leukemia (1 paper, 2016). A neoplasm of lymphoblasts committed to the B-cell lineage, typically composed of small to medium-sized blast cells. "Moreover, expression of p63 and CDK4 is concomitantly up-regulated in B-cell acute lymphoblastic leukemia." (PMID 27341130, 2016).
brain infarction (1 paper, 2025). Tissue necrosis in any area of the brain, including the cerebral hemispheres, the cerebellum, and the brain stem. "Through bioinformatics analysis, we identified key targets associated with cellular senescence and circadian rhythm in cerebral infarction, specifically CREBBP, FOS, CDK4, MMP9, PTEN, and HIF1A." (PMID 40629591, 2025).
carcinosarcoma (1 paper, 2013). A malignant tumor composed of a mixture of carcinomatous and sarcomatous elements.
carpal tunnel syndrome (1 paper, 2023). Entrapment of the median nerve in the wrist that is characterized by numbness, tingling and painful movement. "There are no data of the incidence of carpal tunnel syndrome in patients receiving CDK4/6 inhibitors in the adjuvant setting." (PMID 37293258, 2023).
cartilaginous neoplasms (1 paper, 2024). "Several oncogenic signaling pathways have been implicated in the progression of cartilaginous tumors, such as those related to cell migration (IMP3) and cell cycle (CDK4, MDM2, and β-catenin), which should be better elucidated." (PMID 39368400, 2024).
choriocarcinoma (1 paper, 2022). An aggressive malignant tumor arising from trophoblastic cells. "As p16 is an inhibitor of CDK4 and 6, we assessed the impact of siRNA-mediated silencing of these two kinases on the clonogenic growth of our choriocarcinoma cell lines." (PMID 35301407, 2022). "Increased expression of cyclin-dependent kinase 4 (CDK4) and loss of p16Ink4a in resistant cells suggested that CDK4 inhibition may be a strategy to treat MTX-R choriocarcinoma." (PMID 35301407, 2022).
choroidal tumor (1 paper, 2022). "The choroidal tumor showed regression after the introduction of palbociclib, a cyclin-dependent kinase 4/6 (CDK4/6) inhibitor." (PMID 35962417, 2022).
clear cell carcinomas (1 paper, 2021). "In total, CDK4/6 actionability in patients with high-grade serous, endometrioid and clear cell carcinomas was 41, 41 and 22%, respectively." (PMID 33947352, 2021).
colorectal tumour (1 paper, 2016). "Therefore, miR-491, which is induced in colorectal tumour-bearing mice, may negatively affect the proliferation of CD8+ T cells by targeting CDK4 and TCF-1." (PMID 27484289, 2016).
Congenital hemolytic anemia (1 paper, 2025). A form of hemolytic anemia with congenital onset. "Despite these encouraging results, which suggest that CDK4/6is do not increase RBC fragility or decrease RBC lifespan, one should note that none of these patients had baseline acquired or congenital hemolytic anemia." (PMID 40361493, 2025).
cutaneous malignant melanoma-3 (1 paper, 2021). "Although the etiology of the disease is fully complex including different types of genomic alteration in some genes, e.g. MC1R, CDKN2A, and CDK4, nonfunctional CDK4 is the cardinal hallmark of the disease cutaneous malignant melanoma-3 (CMM3)." (PMID 34735543, 2021).
cystitis (1 paper, 2020). Inflammation of the urinary bladder. "Comparison between different studied groups showed higher values of CDK4 percent and score of expression in malignant tissues (SCC andUC) in relation to cystitis, with statistically significant differences (p<0.001 and p<0.01 respectively)." (PMID 32102537, 2020). "Our studied groups showed higher values of CDK4 and STAT3 expression in malignant tissues (SCC andUC collectively) compared to cystitis, however, significantly higher values of CDK4 and STAT3 expression were detected in UC group compared to SCC group." (PMID 32102537, 2020).
desmoid tumor (1 paper, 2024). A desmoid tumor (DT) is a benign, locally invasive soft tissue tumor associated with a high recurrence rate but with no metastatic potential. "In an alternative approach, the novel CDK4/6 inhibitor ribociclib also showed effects in combination with goserelin and letrozole in a patient with multiple desmoid tumors." (PMID 39411551, 2024).
diffuse astrocytoma (1 paper, 2020). A low-grade (WHO grade II) astrocytic neoplasm. "Attempts to molecularly define the aggressive type of diffuse astrocytomas have suggested several genetic markers such as RB1 pathway alterations (e.g., CDKN2A/B homozygous deletion or CDK4 amplification), PIK3R1 mutation, PDGFRA amplification, or G-CIMP low type in the methylation cluster." (PMID 33228806, 2020).
ductal carcinoma in situ (1 paper, 2024). "Moreover, overexpression of CDK4/6 appears to be an early step in cancer pathogenesis, as early as ductal carcinoma in situ (DCIS) and is maintained during progression to invasive locoregional and metastatic lesions." (PMID 38999983, 2024).
eating disorder (1 paper, 2024). A broad group of psychological disorders with abnormal eating behaviors leading to physiological effects from overeating or insufficient food intake. "Taken together, 17 PAEs were categorized as CDK4/6i‐related PAEs, with eating disorder had the highest ROR value among them." (PMID 39009505, 2024).
embryonal carcinoma (1 paper, 2005). A non-seminomatous malignant germ cell tumor characterized by the presence of large germ cells with abundant cytoplasm resembling epithelial cells, geographic necrosis, high mitotic activity, and pseudoglandular and pseudopapillary structures formation. "In addition, in the embryonal carcinoma cell line NTERA-2, cyclin E-dependent CDK2 activity, but not cyclin D3-dependent CDK4 activity, was suppressed as a result of hexamethylene-bisacetamide-induced differentiation." (PMID 16012517, 2005).
emphysema (1 paper, 2006). "Fifteen genes were thus found to be upregulated in fibroblasts of emphysema, among them IGFBP-rP1 (4.9-fold), LOX (3.3-fold), LOXL2 (3.9-fold) and TIMP3 (3.0-fold), whereas 121 genes were downregulated, among them CDK4 (6.3-fold), FOSL1 (4.8-fold), OAZ1 (6.7-fold) and IGFBP-5 (5.3-fold)." (PMID 16504044, 2006).
endometriosis (1 paper, 2017). The growth of functional endometrial tissue in anatomic sites outside the uterine body. "This study aimed to determine whether arcyriaflavin A, a representative inhibitor of cyclin D1–cyclin-dependent kinase 4 (CDK4), is beneficial in the treatment of endometriosis." (PMID 28720098, 2017).
estrogen-receptor positive breast cancer (1 paper, 2022). "CDK4/6 inhibitors combined with endocrine therapy have demonstrated higher antitumor activity than endocrine therapy alone for the treatment of advanced estrogen receptor-positive breast cancer." (PMID 36071033, 2022).
Familial adenomatous polyposis (1 paper, 2015). Familial adenomatous polyposis (FAP) is characterized by the development of hundreds to thousands of adenomas in the rectum and colon during the second decade of life. "Over-expression of cyclin D1 and CDK4 were evident in the majority of human intestinal adenoma of familial adenomatous polyposis." (PMID 26416244, 2015).
female sterility (1 paper, 2020). "A lack of Cdk4 causes female sterility through suppressing development of the pituitary, resulting in reduced lactotrophs and a deficit in the hypothalamic–pituitary axis, leading to perturbed corpus luteum formation." (PMID 32731332, 2020).
fibroma (1 paper, 2022). A non-metastasizing neoplasm arising from the fibrous tissue.
fibrous tumors (1 paper, 2023). "Ninety percent of benign cases were negative for CDK4 expression, and 10% of cases that showed positive expression were calcifying fibrous tumors (2/3 cases)." (PMID 37016649, 2023).
Fulminant hepatitis (1 paper, 2024). Acute hepatitis complicated by acute liver failure with hepatic encephalopathy occurring less than 8 weeks after the onset of jaundice. "In this series, no patient experienced fulminant hepatitis or death secondary to anti-CDK4/6-induced liver damage." (PMID 38961854, 2024).
Gorlin syndrome (1 paper, 2026). "A sonic hedgehog (SHH)-MB model, including a Gorlin syndrome patient neuroepithelial stem cell line (NES) and its tumor derivative (tNES), was used to evaluate single and combined treatments of PI3K, AKT, FGFR, and CDK4/6 inhibitors (BYL719, AZD5363, JNJ-42756493, and PD-0332991, respectively)." (PMID 41734992, 2026).
gynecologic cancers (1 paper, 2024). "The non-clinical data presented here support the development of gedatolisib combined with CDK4/6 inhibitors and/or hormonal therapy for gynecologic cancer treatment." (PMID 39456616, 2024).
Hearing impairment (1 paper, 2025). A decreased magnitude of the sensory perception of sound. "The selective reporting of hearing and lens disorders with palbociclib, rather than with other CDK4/6is, merits careful consideration for palbociclib use in older patients with baseline hearing impairment or cataract." (PMID 41496429, 2025).